GZMB (granzyme B)
Diseases named in the same sentence as GZMB in open-access papers (continued):
Sharing a sentence is not in itself a finding about the gene and the disease.
tumor (continued). "Importantly, these post-REP TILs retained most of the key features of pre-REP TILs, including a high proportion of GzmB+ cells, and demonstrated potent anti-tumor efficacy upon in vivo administration." (PMID 41280919, 2025). "Interestingly, eliminating Toe-Macs resulted in a significant increase in tumor-infiltrating CD8+ T cells expressing higher amounts of granzyme B (GrB), suggesting that TGF-β1 derived from Toe-Macs suppresses GrB expression, in alignment with prior reports." (PMID 41178715, 2025). "Our study establishes a Tumor Microenvironment-derived Prognostic Model (MPM) that integrates eight TME-associated genes (CXCL12, GZMB, ITPR2, LYN, RAB9B, RGMB, RUFY4, TRIM16) to stratify AML patients into distinct risk categories with significant survival differences." (PMID 40608798, 2025). "Granzyme B can enter the tumor cell through these pores, activating caspase-dependent apoptosis." (PMID 40565031, 2025). "In the meantime, MHC‐I blocking could partly hinder the recovery of tumor‐infiltrating CD8+ CTLs (both IFN‐γ+CD8+ CTLs and GZMB+CD8+ CTLs) caused by MARCO‐knockdown TAMs, which is consistent with the in vitro findings." (PMID 41117057, 2025). "However, the proportion of granzyme B in tumour cells was impaired in the combination therapy group compared to the oHSV group." (PMID 39219056, 2025). "Additionally, the expression of CD80, CD107α, and Granzyme B in tumor-infiltrating lymphocytes is significantly upregulated, directly confirming enhanced T cell activity and cytotoxic function." (PMID 41400642, 2025). "Moreover, the significant infiltration of CD8+ T cells and increased release of IFN-γ and granzyme B in liver and spleen provide evidence of enhanced anti-tumor activity by CD8+ T cells, compared to control group." (PMID 40308579, 2025). "In addition, hypoxia-induced autophagy inhibits NK-mediated killing and degrades NK-derived Granzyme B (GrzB), reducing immunotherapy effectiveness by decreasing CTLs-mediated tumor cell lysis and pSTAT3 phosphorylation." (PMID 40422248, 2025). "GZMB is specifically expressed in cancer cells undergoing EMT at the tumor invasion front." (PMID 41567188, 2025). "The qRT-PCR analysis of tumor tissues showed that the Flagrp170-Her/neu vaccination was more efficient than the conventional Grp170 chaperone vaccine in upregulating the immune genes ifng and granzyme B." (PMID 41295469, 2025). "EphA2 CAR-T cells showed higher killing efficiency of A549 cells and increased secretion of IFN-γ, TNF-α and granzyme B. In contrast, studies in xenograft mouse models confirmed that A549 tumor growth was suppressed and the number of cells infiltrating the tumor had elevated." (PMID 40428391, 2025). "Several studies have demonstrated a positive role of GZMB in suppressing tumor activity." (PMID 40002821, 2025). "TIIC-related markers, including CD3, CD8a, and GZMB, represent T-cell killing of tumor cells." (PMID 39781264, 2025). "The release of IFN-γ, TNF-α, and GZMB further enhanced tumor cell killing." (PMID 40281554, 2025). "Additionally, in anti-TIGIT antibody-treated spleens, there were more NK (CD3e–NK1.1+NKp46+) cells within the CD45.1+ tumor immune environment and concomitantly greater NK cell activation (as indicated by granzyme B expression) following anti-TIGIT treatment." (PMID 40111422, 2025). "Importantly, the G&P group showed a significant presence of densely distributed Granzyme B-positive granules across the tumor tissue." (PMID 41488675, 2025). "More importantly, HDAC2 inhibitors not only inhibit nuclear PD-L1 translocation, enhancing the efficacy of PD-1/PD-L1 checkpoint inhibitors, but also significantly increase the proportion of CD8+ and CD8+GranB (granzyme B)+ cells within tumor-infiltrating lymphocytes." (PMID 40573881, 2025). "As recent discoveries have shown, tumor growth and immune evasion during cancer development may depend on the activity and expression of granzyme B (GZMB) in immune cells." (PMID 40766321, 2025).
tumor (continued). "Fu and colleagues revealed that sEVs released by CAR-T cells (CAR-T-sEVs) carry multiple cytotoxic molecules (Granzyme B and perforin) and could suppress tumour growth in xenograft models, likely via direct tumour killing." (PMID 40560407, 2025). "In this context, we found that tumor-associated PD-1+ trNK cells from MSI CRCs, as well as PD-1– trNK cells from MSI and MSS CRC, were characterized by adequate amounts of activating NK receptors and a moderate but consistent content of perforin/granzyme B, to exert anti-tumor activities." (PMID 40607422, 2025). "The RNAseq results provided additional support of the CD8 and granzyme B IHC data and suggested that Th1 response might be enhanced in the post-treatment tumor microenvironment due to up-regulation of IFNg and TBX21 gene expression." (PMID 39965362, 2025). "In addition, ROR1-reactive HTLs produce granzyme B, which directly induces tumor cell death, as confirmed by their cytotoxicity against ROR1+ HNSCC cell lines." (PMID 40723210, 2025). "Furthermore, exosomes from activated T cells carry TNF-α and granzyme B, contributing to the elimination of tumor cells through cytotoxic mechanisms." (PMID 40693234, 2025). "In the acidic lysosomal environment, these nanoparticles disassociated, releasing perforin and granzyme B. Upon recognition of tumor cells by T cells, the lysosomal contents are discharged to the immunological synapse, enabling precise and efficient tumor cell killing." (PMID 41049749, 2025). "CIK cells, primarily consisting of CD3+CD56+ T-cell subsets generated by stimulation with IFN-γ, IL-2, and anti-CD3 monoclonal antibodies, mediate tumor cell killing through both the perforin/granzyme B pathway and death receptor-mediated signaling such as Fas/FasL." (PMID 40904467, 2025). "However, the pro-apoptotic effect of GZMB is suppressed, potentially contributing to tumor progression." (PMID 41567188, 2025). "Granzyme B (GZMB), also known as granzyme β, is a caspase-like serine proteolytic enzyme, released from granules of natural killer cells (NK cells) and cytotoxic T cells to kill virus-infected and tumor cells." (PMID 40766321, 2025). "Stimulates γδT cells to secrete granzyme B and perforin, enhancing tumor killing." (PMID 41181090, 2025). "Notably, granzyme B production in the tumor microenvironment was nearly doubled in the essential oil-treated group." (PMID 40429884, 2025). "Consequently, the combination therapy led to a further increase in granzyme B production within the tumor." (PMID 39721027, 2025). "Moreover, tumor cells frequently express PI-9, a natural antagonist of GZMB, which binds to its active site and completely neutralizes it, thereby nullifying its tumor-killing effect." (PMID 41567188, 2025). "Additionally, cytokines within the TME and endogenous inhibitors within these cells precisely regulate the expression and activity of GZMB, thereby adding further complexity to its role in tumor progression." (PMID 41567188, 2025). "Similarly, there was a significant increase in the accumulation of GzmB+ cells in CT2A tumor tissues following cinobufagin treatment." (PMID 39901195, 2025). "In order to infer fate trajectories of these different phenotypes that were clonally linked by a common TCR barcode, pseudotime analysis by Monocle was carried out specifically on cells with tumor-blood-matched TCRs from GZMB+, GZMK+, CXCL13+, Tregs, Prolif, and MAIT populations." (PMID 40299576, 2025). "In addition, compared to WT mice, GPR132-deficient mice exhibited a higher survival rate, an elevated number of tumor-infiltrating NK cells, which expressed more granzyme B (GzmB) and IFN-γ." (PMID 40043109, 2025). "Studies on tumors in these organs have shown that CD103+ T cells could release cytolytic granules containing perforin and granzyme B (GZMB) to directly kill tumor cells, which allows tumor antigens to be used for the activation of new tumor‐specific T cells." (PMID 41388658, 2025).
tumor (continued). "Furthermore, our in vitro and in vivo results demonstrated that TZ‐dSA3‐12 strongly induced the surface expression of CD80 and CD86 on DCs within the tumor microenvironment, and boosted the production of IFN‐γ and GzmB by tumor‐infiltrating CD8+ T cells." (PMID 40492586, 2025). "Autophagy has been shown to play a role in multiple mechanisms of tumor immune evasion, including avoidance of destruction by cytotoxic T cells, degradation of cytotoxic granules such as granzyme B and perforin, and reduction of immune recognition of tumor antigens." (PMID 40457397, 2025). "Notably, depletion of ASNS also increased the infiltration of CD8+ T cells in tumor parenchyma and enhanced their cytokine production including GZMB, TNF-α, and IFN-γ." (PMID 39964752, 2025). "Consequently, substantial evidence indicates that a variety of immune cells, including Tregs, MDSCs, pDCs, Bregs, and mast cells, as well as tumor cells themselves, can express GZMB." (PMID 41567188, 2025). "The powerful CD103+TCF1+ TRM cells then mediate efficient tumor eradication through secretion of the T cell effector cytolytic granules perforin and granzyme-B after their infiltration into the remaining tumor tissues (in peripheral areas of tumor masses) with IRE+Combo-induced TME modulation." (PMID 41194931, 2025). "This may imply that GZMB in Treg plays a more complex role, not only in the elimination of tumor cells, but also in the modulation of the immune response." (PMID 40766321, 2025). "In immunocompetent mouse models, administration of the PDPN-targeting inhibitory peptide CY12-RP2 enhanced T cell infiltration and increased the cytotoxic activity of CD8+Granzyme B+ T cells, which are fundamental for perforin–granzyme B-dependent tumor cell lysis." (PMID 41573582, 2025). "Specifically, they found that acetic acid derived from B. thetaiotaomicron can induce M1 macrophage polarization in HCC, thereby increasing the secretion of CD8+T cells, IFN-γ, and granzyme B by cytokines and ultimately enhancing T cell-mediated tumor cell killing." (PMID 40070843, 2025). "In vivo experiments: Utilizing humanized or immunocompetent IBC mouse models to evaluate the effects of SPP1 knockout or anti-SPP1 neutralizing antibodies, as well as depletion of pDCs or inhibition of their GZMB activity, on tumor growth, metastasis, and treatment response." (PMID 41567210, 2025). "The hypothesis that niches expand at the same rate conflicts with the progressive increase in the prevalence of IFN-responsive cancer cells, C1q macrophages, and activated GzmB+ Tc during tumor progression." (PMID 41280683, 2025). "The increased tumor suppression by Usp22 deletion is associated with increased tumor cell surface H-2Kb and β2M expression, the elevated tumoral-infiltrating CD8+ T cells and their production granzyme B, IFN-γ, and TNF-α." (PMID 41252204, 2025). "The utilization of nanoprobes enables the concurrent administration of an immune checkpoint inhibitor (αPDL1) and imaging probe to the tumor area, facilitating timely monitoring of time‐sensitive granzyme B activity as a direct method for early assessment of immunotherapy efficacy." (PMID 40585764, 2025). "It is also worth noting that while granzyme B secreted by DCs can contribute to tumor cell apoptosis, it may also exert suppressive effects on T-lymphocytes." (PMID 40725022, 2025). "Furthermore, in CD8 T cells, perforin and granzyme B, which are cytotoxic mediators that directly induce tumor cell death, were highly expressed by DAF." (PMID 41011224, 2025). "Other reported effects of smoking on T cells, that may impair anti-tumor immunity and surveillance, include the suppression of Granzyme B expression in CD8+ T cells, reduced activation of cytotoxic T lymphocytes, and promotion of senescence and exhaustion." (PMID 40231254, 2025). "Until recently, it was believed that GZMB activity protects us from cancer or reduces tumor activity, but data are emerging that may challenge this." (PMID 40766321, 2025).
tumor (continued). "The results indicate that GBM has high GZMB expression, which may be related to an intense immune response at the level of the tumor microenvironment." (PMID 40766321, 2025). "Furthermore, increased levels of cytotoxic granules (Granzyme B and Perforin), anti-tumor cytokines (IFN-γ and TNFα), and the apoptotic marker CHOP/GADD153 were observed in MerTK-overexpressing tumors in both ICI treatment groups by IHC." (PMID 40391157, 2025). "Interestingly, knockdown of Cxcl3, but not of Ccl20, notably increased the frequency and activity of tumor-infiltrating granzyme B+ (GzmB+) CD8+ T cells." (PMID 40179015, 2025). "Moreover, mIHC analysis of six HCC patient samples revealed that the levels of CD8+ T-cell infiltration and GZMB secretion were strikingly greater in TACC3-low tumor samples than in TACC3-high tumor samples." (PMID 40866361, 2025). "MMP13 is also positively correlated with CD8+T infiltration, which specifically identifies tumour-associated antigenic peptides presented on cell surfaces and mediates cytotoxic effects through the release of IFN-γ, granzyme B, and perforin, ultimately inducing tumour cell lysis." (PMID 40243781, 2025). "Notably, the synergistic effect of the gold center and GLA downregulates PD‐L1 expression in tumor cells and enhances granzyme B (GzmB) expression in T cells." (PMID 40842087, 2025). "While we did observe increased frequencies of Granzyme B+ (GzmB+) T cells in the IL-2–expanded group compared with those expanded with IL-7, we also noted an increased baseline frequency of GzmB+ T cells in the unstimulated/IL-2–expanded and tumor-only control groups." (PMID 40244705, 2025). "These UniCAR T cells produced granzyme B (GZMB) to kill tumor cells." (PMID 40704837, 2025). "Additionally, the results from the multiple immunofluorescence analysis of NUAK1, CD8α, and GZMB demonstrated that the overexpression of NUAK1 markedly decreased the population of GZMB+ CD8+ T cells within the tumor microenvironment." (PMID 39901136, 2025). "In addition, cytotoxic T cells (CTL) release cytotoxic molecules, such as granzyme B, to exert functions of killing tumour cells." (PMID 39219056, 2025). "In the analysis of antitumor immunity using the tumor tissues of both sides harvested 14 days after the first OBP-702 injection, the combination therapy of butyrate and OBP-702 tended to increase CD8 + T cells, CD8 + IFN-γ + T cells, and Granzyme B expression in the tumor tissues on both sides." (PMID 41410712, 2025). "Overall, GZMB+ cells comprised the majority (~50%) of circulating CD4+ cells with tumor-matched TCRs, and GZMB+ and GZMK+ cells together represented more than 40% of intratumoral CD4+ cells with blood-matched TCRs despite these cells constituting the minority of total CD4+ cells." (PMID 40299576, 2025). "Moreover, 6d exhibits a synergistic effect of gold center and GLA, suppressing programmed cell death 1 ligand 1 (PD‐L1) expression in tumor cells while promoting granzyme B (GzmB) production in T cells." (PMID 40842087, 2025). "In tumor, IFNγ levels and Granzyme B expression were also increased, a fact that might indicate a shift to a pro-inflammatory microenvironment derived from the inactivation of Tregs by ILs." (PMID 39075226, 2025). "Cytotoxic CD4+ circulate between the blood and tumor of bladder cancer patients, where they exist as clonally related but distinct pools of granzyme B+ effector cells dually inhibited by PD-1 and KLRG1, and effector memory granzyme K+ cells that are not mobilized by PD-1 blockade." (PMID 40299576, 2025). "GZMB’s role in tumor immunity is exceptionally complex and contradictory." (PMID 41567188, 2025). "Notably, the combination of a gold center with GLA prevents tumor cells from expressing PD‐L1 and promotes T cells to produce GzmB." (PMID 40842087, 2025). "Furthermore, CD8+ T cells from simvastatin‐treated mice displayed significantly higher Ki67 and increased expression of granzyme B, the executor of tumor cell killing." (PMID 40820860, 2025).
tumor (continued). "The enhanced anti-tumor effect of ISCU-deficient macrophages appeared to be dependent on increased CD8+ T cell infiltration and their augmented anti-tumor activity (e.g. TNF-α, IFN-γ and Granzyme B secretions) within the tumor microenvironment." (PMID 40541964, 2025). "Importantly, MSC-sourced IL-15 not only enhances viability and expansion of NK cells, but also up-regulates expression of cytotoxic molecules (perforin, granzyme B, and Fas ligand (FasL)), thereby augmenting their ability to directly kill tumor cells." (PMID 40643499, 2025). "However, our current chronic HS diet treatment has shown a blunting of effector anti-tumor immune responses, as evidenced by the reduced expression of cytotoxic granzyme B and IFNγ in CD8+ and CD4+T cells." (PMID 38891044, 2024). "We designed and validated reporters to directly assay T cell delivered GZMB activity in tumor cells and confirmed that while PI9 overexpression inhibits GZMB activity at the molecular level, this is not sufficient to impact the kinetics or magnitude of killing mediated by the CAR T cells." (PMID 38307835, 2024). "Furthermore, the cytotoxic function of CD8+T cells was enhanced in Mn‐N/C‐treated tumors, as evidenced by elevated production of cytotoxic molecules IFNγ and Granzyme B in the tumor‐infiltrating CD8+T cells after Mn‐N/C treatment." (PMID 38308189, 2024). "IFN‐γ is cytotoxic and initiates apoptosis in tumor cells together with Granzyme B and perforin." (PMID 38553868, 2024). "The functionally activated CD107a+ NK cells use perforin and GzmB as granule-mediated cytotoxicity against target tumour cells as an early stage of effect, while NK cells subsequently switch to CD95L death-receptor-mediated cytotoxicity as a final stage of cell killing." (PMID 38893071, 2024). "In addition, knocking out Rig-I enhanced the secretion of anti-tumour cytokines such as CD107a, perforin, granzyme-B, IFN-γ, and TNF-α by CD8+ T cells." (PMID 39322862, 2024). "Additionally, immune cells attracted by chemokines, such as CXCR3 and CCR5/4, can induce apoptosis in tumor cells through the secretion of effector cytokines, such as granzyme B, which exert a cytotoxic effect and elicit an antitumoral response." (PMID 39769501, 2024). "Moreover, the levels of total and activated CD8+ cytotoxic T cells (GzmB+) that infiltrated the tumor microenvironment were significantly increased in the AUY-922 treated group." (PMID 38762492, 2024). "Granzyme B plays a significant role in inducing apoptosis in tumor cells." (PMID 38339258, 2024). "Notably, single-cell data showed higher proportions of granzyme B+ B cells in tumor samples compared to control samples, and these levels were positively associated with disease-free survival." (PMID 38386050, 2024). "Given that CD8 + cytotoxic T lymphocytes (CTLs) eliminate cancer cells by secreting Granzyme B (GB), a potent inducer of tumor cell apoptosis, we investigated the CD8 + CTL population and CTL activity by measuring GB release in xenograft CT26 tumors using immunofluorescence analysis." (PMID 38383447, 2024). "PDCs can secrete granzyme B, which can eliminate tumor cells through its cytotoxic effect." (PMID 38927922, 2024). "Additionally, low-dose chemotherapy sensitizes tumor cells to CAR-T cell activity by facilitating the penetration of granzyme B into the tumor cells." (PMID 39335671, 2024). "It has been established that Sb9 can protect tumor cells from GzmB mediated destruction, whether GzmB originates from cytotoxic lymphocytes or is produced endogenously." (PMID 38966643, 2024). "Using isolated tumor tissue, we analyzed gene expression related to cytotoxicity (Perforin, Granzyme B, Granulysin, and FasL), inflammatory or chemotactic cytokines (IFN-γ, CXCL9, CXCL10, and CXCL11), and CD8+ T cell activation and proliferation (CD69, Tbx21, IL-2, and IL-12b)." (PMID 39066478, 2024).